RNU1-1 (RNA, U1 small nuclear 1)
Synonyms: Rnu1a1; U1; HU1-1; U1A1; HSD1; RNU1; RNU1A; RNU1A3; RNU1G4
Gene: Small nuclear RNA gene on chromosome 1 (16,514,122 to 16,514,285, reverse strand). Ensembl gene ENSG00000206652.
Pathways (Reactome):
Gene expression (Transcription): RNA polymerase II transcribes snRNA genes
Gene Ontology:
Molecular function: pre-mRNA 5'-splice site binding
Biological process: mRNA 5'-splice site recognition
Cellular component: U1 snRNP
Homologues: Orthologues: chimpanzee U1 (100% identical), pig U1 (100% identical). Paralogues in human: RNU1-2 (100% identical), RNU1-27P (100% identical), RNU1-28P (100% identical), RNU1-3 (100% identical), RNU1-4 (100% identical), RNVU1-18 (100% identical), RNVU1-29 (100% identical), U1 (100% identical), RNVU1-28 (99% identical), RNVU1-7 (99% identical), RNVU1-31 (99% identical), RNU1-89P (97% identical), and 134 more.
Diseases named in the same sentence as RNU1-1 in open-access papers:
RNU1-1 is named in the same sentence as 10 diseases in open-access papers, as found by Europe PMC text mining. Sharing a sentence is not in itself a finding about the gene and the disease. The quoted sentences say what the papers report.
microcephaly (2 papers, 2022 to 2023). A congenital or acquired developmental disorder in which the circumference of the head is smaller than normal for the person's age and sex.
microcephalic osteodysplastic primordial dwarfism (1 paper, 2022). "RNU11 gene belongs to the snRNA class, and the mutation in this gene is associated with Microcephalic Osteodysplastic Primordial Dwarfism, Type I." (PMID 35436926, 2022).
PRLomas (1 paper, 2019). "However, PLS-DA analysis neatly revealed a different expression pattern between PRLomas and NPs, and VIP score analysis identified three components with high capacity to discriminate between both populations (RAVER1, MAGOH, and RNU11)." (PMID 31561558, 2019).
RNU1-1 also shares sentences with these, for which no sentence is quoted: Tumor (3 papers); asthma (1); cancer (1); colorectal cancer (1); leukemia (1); myeloma (1); prostate carcinoma (1).